IL6 (interleukin 6)
Diseases named in the same sentence as IL6 in open-access papers (continued):
Sharing a sentence is not in itself a finding about the gene and the disease.
tumor (continued). "TAM generates many immunosuppressive factors and chemokines, including IL-6, IL-10, TNF-α, TGF-β, etc., which decrease antigen presentation and impair T cell activity, allowing tumor cells to elude the body’s immunological surveillance." (PMID 34922542, 2021). "Pro-tumorigenic role: TLR is able to send its pro-tumorigenic signals in tumor cells or in TME by enhancing NF-kB, which, in turn, activates its cascade made up of IL-1β, TNF-α, IL-6." (PMID 34944856, 2021). "Tumor cells can self-sustain this supportive environment by producing inflammatory cytokines like TNF-α, IL-1β, and IL-6." (PMID 34322780, 2021). "Overexpression of IL-1β leads to enhanced metastasis (one of the major causes of adverse prognosis in patients with advanced OSCC) through secretion of oncogenic cytokines IL-6, IL-8, and GRO-α (growth-regulated oncogene α) by tumor cells." (PMID 34442627, 2021). "Overall, these data suggest that tumour spheroids and 3D microfluidic models closely resemble the physiological TME, and that IL6 provides a therapeutic target to decrease the metastatic potential of cancer cells that survive acidosis." (PMID 34831016, 2021). "Activated astrocytes, in turn, produce IL-6, TNF-α, and IL-1β, which promote tumor cell proliferation." (PMID 33466236, 2021). "Apart from the recruitment of tumor-infiltrating B cells, CXCL13, expressed by interleukin-6 (IL-6)-treated human bone marrow endothelial (HBME) cells, mediates PC-cell invasion, adhesion to HBME cells, and αvβ3-integrin clustering." (PMID 34947813, 2021). "In fact, macrophages produce proinflammatory cytokines, such as TGF-β, IL-6, IL-10, and TNF-α, that induce stem cell-like characteristics in tumor cells, thereby sustaining these tumor cells and allowing them to continue to grow." (PMID 34502312, 2021). "TAMs modulate the CCA microenvironment by secreting TNFα, TGFβ (tumor growth factor-β), IL6, IL10, and VEGF-A (vascular endothelial growth factor-A), which support epithelial-to-mesenchymal transition (EMT), tumor growth, and metastasis." (PMID 33579265, 2021). "Pro-inflammatory M1-like macrophages, differentiated by lipopolysaccharide (LPS) and interferon-γ (IFN-γ), exhibit the ability of anti-tumor functions to secrete the pro-inflammatory cytokines (e.g., TNF-α, IL-6, IL-12, and IL-12)." (PMID 34576180, 2021). "Herein, we provide the first evidence that ANXA1 is a positive regulator of tumor growth and metastasis in PTC, complementing its biological function via influencing the dynamic properties of EMT and regulating IL-6/JAK2/STAT3 signaling network." (PMID 33531975, 2021). "The expression of IL-6 and of TGF-b by tumor cells has a significant role in primary adhesion between MSCs and cancer." (PMID 35111750, 2021). "IL-6 and OSM are clear EMP promoters and their role in tumour progression and metastasis is widely accepted." (PMID 34361105, 2021). "IL6 has also been shown to promote EMT, tumor cell invasion, and drug resistance to tyrosine kinase inhibitors in NSCLC." (PMID 34944848, 2021). "In a dose-dependent manner, it inhibited tumor cell proliferation, promoted macrophage proliferation and the expression of TNF- and IL-6 secretion, TLR2 and TLR4, and stimulated macrophage phagocytosis through the release of NO and H2O2." (PMID 33435246, 2021). "In the tumor microenvironment, TAMs secrete many cytokines such as TGF-β and IL-6 that can induce EMT." (PMID 33922795, 2021). "Like these pro-inflammatory cytokines (TNF-α, IL-6, and IFN-γ), HA is another principal constituent in the stromal tissues surrounding tumor tissues." (PMID 34770956, 2021). "miR-223-3p repression led to increased expression of tumor supportive cytokines VEGF and IL6 and inhibition of the osteogenic potential of MM-MSCs, as indicated by reduced expression of RUNX2 and OPN, as well as reduced calcification and ALPL activity." (PMID 33673480, 2021).
tumor (continued). "IL6 secretion then conferred PD-L1 expression on neutrophils, reduced CD3+ T cell proliferation, and reduced response to tumor immunotherapy." (PMID 34248988, 2021). "MAFs can also augment tumor cell resistance to chemotherapy drugs by producing cytokines, including IGF2, IL-6 and IL-8." (PMID 34112258, 2021). "STAT-3 promotes the transcription of factors involved in inflammation (IL-6, IL-11, and IL-1β), angiogenesis (VEGF), invasion (MMPs), and regulators of cell proliferation (cyclin D1, MYC), all of which mediate pro-tumour effects." (PMID 34944729, 2021). "Overexpression of IL6 reduces methylation of the EGFR promoter and enhances EGFR expression, leading to tumor growth promotion." (PMID 33579265, 2021). "Intriguingly, IL-6 secretion seems to be directly dependent on the acid-stimulated MSC, whereas the tumour cells contribute little to the release of paracrine tumour-stimulating factors under acidic pH conditions." (PMID 34359749, 2021). "In this context, the serine-threonine protein kinase (STK) 4 counteracts TLR signalling and concomitant IL-6 secretion through phosphorylation of the TLR downstream signalling molecular IRAK1 and is therefore considered as tumour suppressor for HCC." (PMID 34047814, 2021). "In vitro analysis highlighted an immunosuppressive cytokine profile in tumour involved lymph nodes consisting of higher levels of IL6, IL10, and TNFα released under stimulation, while IFNγ release was high in cells from tumour free lymph nodes." (PMID 34640541, 2021). "Saline-treated tumor-bearing mice demonstrated a marked, though statistically insignificant, increase in serum IL-6 and TNF-α compared to tumor-free mice." (PMID 34445729, 2021). "Macrophages have two phenotypes, M1 and M2, among which M1 cells are pro-inflammatory cells, producing a variety of inflammatory cytokines, such as IL-6, IL-12, and TNF-α, which play an important role in anti-tumor immunity." (PMID 34721019, 2021). "In the present study, we also observed a positive correlation between IL6 expression in tumors and BCL3 expression in tumor-adjacent samples of ESCC patients, suggesting a possible dysregulation of this axis in the early stages of esophageal carcinogenesis." (PMID 34422669, 2021). "Cytokine measurements showed that the serum levels of IL-6, IL-1 and TNF-ɑ were all elevated in CT26 tumor-bearing mice compared with normal control mice." (PMID 34724970, 2021). "STAT3-activating cytokines (e.g., IL6, IL10, VEGF) secreted by tumor cells promote abnormal dendritic cell differentiation and globally suppress dendritic cell maturation and activation." (PMID 34944848, 2021). "IL-6 activates STAT3, which has previously been shown to enhance tumor cell growth, resistance to chemotherapy, and tumor dissemination in some tumor types." (PMID 34209460, 2021). "Several lines of evidence demonstrate that the autocrine/paracrine IL‐6/JAK/STAT3 feed‐forward loop participates in tumor progression and shapes of the tumor microenvironment." (PMID 34375503, 2021). "STAT3 has been described as a master transcriptional factor that drives tumor progression of multiple cancers via regulating the expression of key target genes such as VEGF, MMP and IL-6." (PMID 34930899, 2021). "Blockade of IL-6 with tocilizumab and STAT3 knockdown attenuated CD44+ sphere formation and tumor growth of patient-derived HCC as well as breast xenografts." (PMID 34235155, 2021). "Among the inflammatory mediators, cytokines IL-1α, IL-1β, IL-6, and IL-8 and chemokine CXCL10 were highly expressed, suggesting a function of CAFs in tumor-mediating inflammation." (PMID 34298873, 2021). "IL6 is one of the most abundant inflammatory mediators in TME and is reported to promote EMT and subsequent tumour progression and metastasis." (PMID 34936736, 2021). "In our study, secretion of IL-6, IL-8, MMP-9, PDGF-BB, IL-1β, G-CSF, and CCL-2 by ccRCC immune cells in tumor microenvironment were able to overcome the anti-angiogenic effects of cabozantinib." (PMID 34931665, 2021).
tumor (continued). "For instance, it has been shown that STAT3, a downstream target of the IL-6 signaling pathway, induces the expression of target genes including VEGF and bFGF in TAMs and MDSCs, thereby contributing to tumor angiogenesis." (PMID 34671021, 2021). "HSP72 exposed on tumor-derived exosomes binds to TLR2 on MDSCs and triggers STAT3 signalling, promoting IL6 expression and immunosuppressive activity." (PMID 33544155, 2021). "CAFs can produce an array of growth factors and cytokines (TGF-β, FGFs, HGH, IL-6 and LIF) providing strong evidence for paracrine signaling between CAFs and tumor cells which is integral to tumorigenesis." (PMID 34858425, 2021). "MM-MSC-EVs express high levels of IL6, CCL2, and fibronectin and low levels of the tumor suppressor mir15a." (PMID 33923357, 2021). "Taken together, these findings indicated that miR-155-5p transferred by M2 macrophage-derived exosomes promoted the expression of IL-6 expression through downregulation of ZC3H12B, thus inhibiting T cell immune response and promoting tumor formation." (PMID 33718596, 2021). "For proinflammatory cytokines, a decreasing trend is also observed with IL-6 and INF-γ within the EE group tumours compared to the SE group (respectively)." (PMID 35008220, 2021). "IL-6 produced in the TME activates the JAK/STAT3 signaling pathway, favoring tumor growth and metastasis." (PMID 34552929, 2021). "The levels of TNF-alpha (p<0.0001), IL-6 (p = 0.027), IL1-beta (p<0.0001) and MCP-1 (p<0.0001) in the tumor microenvironment were positively correlated with OSCC volume." (PMID 33411841, 2021). "Pro-inflammatory cytokines such as IL-1, IL-6, IL-8, IFN-γ, TNF-α, on one side are responsible for the growth and proliferation of immune and tumor cells, while on the other hand, increase tumor immune surveillance programs." (PMID 33924500, 2021). "Conversely, viable tumor cells export HSP70 in exosomes which showed to activate myeloid-derived suppressor cells (MDSCs) and macrophages for the production of IL-6 and TNF-α, respectively." (PMID 33815422, 2021). "There is a CD38+ M1 macrophage population in TME that produces high levels of IL-6 and TNFα with concomitant CD80 expression, prompts more inflammation and helps in tumor suppression." (PMID 33727923, 2021). "Combined blockade of IL-6 and CTLA-4 suppressed lung tumor growth in mice by increasing tumor-infiltrating CD8+ T cells and M1 macrophages." (PMID 34093869, 2021). "In this study, we found that compared with the tumor group alone, the NK-exosome-treated tumor group exhibited a significant decrease in the expression of CD133, Bmi-1, MMP-3, IL-1β, IL-6, and TNF-α." (PMID 34527741, 2021). "The CD4+ Th cells modulate tumor microenvironment by secreting cytokines such as IFN-γ, TGF-β, IL-4, IL-5, and IL-6." (PMID 33995619, 2021). "The enrichment of pro-fibrogenic and pro-inflammatory cytokines (IL-1β, IL-6 and IL-8), acute phase proteins (CP and SAA1), and growth factors (AREG and EREG) in CAFs by tumour cells was shown earlier in an LX-2 HepaRG transwell model." (PMID 34885024, 2021). "Collectively, IL-6/JAK/STAT signaling pathway plays a fundamental role in tumorgenesis and immunosuppressive tumor microenvironment." (PMID 35155571, 2021). "Thus, IL-6 is possibly involved in alterations of immune responses in the tobacco-smoke airways triggering chronic inflammation capable to induce cell transformation and subsequent tumor growth as well as being involved in allergy, asthma and other pulmonary diseases." (PMID 33216184, 2021). "Of note, alternatively activated macrophages and MDSCs are a major source of STAT3-activating cytokines such as IL6 and IL11, which form a paracrine loop to perpetuate a tumor-reactive microenvironment by acting on cancer cells." (PMID 34944848, 2021). "Further evidence of reduced immunosuppression following the combination therapy was a significant decrease in pro‐tumor cytokines, such as IL‐6 and CXCL‐1 in the serum of tumor‐bearing mice (Fig EV4E)." (PMID 33283987, 2021).
tumor (continued). "In contrary, A-FABP knockdown or anti-IL-6 significantly decreased the STAT3 phosphorylation level in macrophages, subsequently inhibiting the tumor colony formation and metastasis." (PMID 33957948, 2021). "Garcinia livingstonei T. Anderson (GLT) elevates the expression level of iNOS and IL-12, and reduces the expression levels of IL-6, TNF-α, Arg-1, and IL-1β on TAMs to impede the tumor progression through the inhibition of STAT3, JNK, and ERK signaling pathway." (PMID 33748122, 2021). "IL-6 is produced in response to local proinflammatory cytokines such as TNF-α, within the tumor microenvironment and can activate JAK/STAT3, MAPK, and PI3K/AKT pathways." (PMID 34912809, 2021). "IL-6 is a pro-tumorigenic cytokine that triggers JAK/STAT3 activation, which promotes tumor cell growth and suppresses tumor cell apoptosis." (PMID 33925400, 2021). "VDR activation of the stromal fibroblast using calcipotriol, a vitamin D analog, diminished expression of genes involved in growth factors and cytokines, for instance, the IL6 and POSTN, thereby suppressing a tumor-promoting secretome." (PMID 34760886, 2021). "The level of IL-6 was elevated in the TME of a prostate cancer model due to TAM activation and tumor cell secretion induced by β-AR signaling." (PMID 34869378, 2021). "The inflammatory cytokines, including interleukin-6 (IL-6), tumor necrosis factor-alpha (TNF-α), and transforming growth factor-beta (TGF-β) play critical roles in tumor progression and promote early metastasis." (PMID 33685460, 2021). "Surprisingly, we found that the therapeutic concentration of DIM upregulated the expression level of tumor-related factors such as CCL-2, IL-6, and IL-8 in GC-MSCs." (PMID 33842314, 2021). "IL-6, CXC-chemokine ligand (CXCL) 9, and TGF-β, which are produced by CAF, have well-established roles in suppressing anti-tumor T cell responses." (PMID 34094963, 2021). "VPA/HPTA treatment alone significantly promoted an increase in the cell population expressing M1 marker (CD86; P <0.01) and M1 function markers (IL-12, IL-6, MHC-II, IFN-γ and TNF-α; P <0.01) at the transcriptional level in the tumor." (PMID 34054811, 2021). "In the tumor microenvironment, IL6/JAK/STAT3/SIGNALING played an important role in promoting the proliferation and metastasis of tumor while strongly inhibiting the antitumor immune response." (PMID 34712264, 2021). "By contrast, the NK-exosome-treated tumor group exhibited a significant reduction in Bmi-1, MMP-3, IL-1β, IL-6, TNF-α, Bax, Bcl-xL, and PCNA expression compared with that in the tumor group." (PMID 34527741, 2021). "TAF-derived cytokines (such as IL-6 and SDF-1A) can induce MDSC generation and activation, and then weaken the human anti-tumor immune response, thus creating favorable conditions for the development of HCC." (PMID 34869376, 2021). "Another strategy tested to achieve tumor remission was the inhibition of CD10+ and GPR77+ CAFs by IL-6 and IL-8 antibodies or anti-GPR-77 antibodies in combination with docetaxel in a xenograft model." (PMID 33806802, 2021). "Some cytokines that are involved in inflammation response, including IL‐1β, IL‐6, TNF, and C‐reactive protein (CRP), are increased in depressed patients and promote tumor progression." (PMID 34723436, 2021). "Combined targeting of IL-6 and the PD-1/PD-L1 axis has shown reversal of immunosuppression in the TME leading to immune activation and tumor rejection in murine models of human cancer." (PMID 34335558, 2021). "Lately, a novel synergistic immunotherapy strategy based on dual targeting of IL-6 and CD40 has been proposed to potentiate anti-tumor immunity in animal GBM models." (PMID 34439380, 2021). "Consistently, increased levels of circulating pro-inflammatory cytokines, such as TNF-α, IL-6 and MCP-1, have been reported in cachectic tumor-bearing mice, as well as in cancer patients." (PMID 33671024, 2021).
tumor (continued). "Several studies including ours reported that CAFs-secreted cytokines including IL-6, IL-8, TGF-β, and IL-1β participated in tumor progression through holding communication between CAFs and cancer cells." (PMID 34930899, 2021). "IL-6 was also shown to promote HNSCC tumorigenesis by activating fibroblasts and increasing tumor cells–CAF crosstalk." (PMID 33925575, 2021). "Here, we highlight several cytokines that are closely related to tumor immunotherapy, including IFN-γ, IL6, IL17, TGF-β." (PMID 34722510, 2021). "Of those patients with a low IL-6 who died, or developed recurrent RCC disease (n = 10), only one had a RCC tumor < 7 cm at diagnosis." (PMID 32621022, 2021). "In PC models, STAT3 activity in tumor-infiltrating MDSCs correlated to increased PD-L1 levels and elevated plasma levels of IL6-type cytokines, such as LIF, suggesting a potential cross-talk mechanism promoting tumor immune evasion." (PMID 34945784, 2021). "In this regard, NEAT1 has been shown to strengthen IL-6/STAT3 signaling and promote tumor growth and proliferation through nuclear trapping of mRNAs and proteins which acts as inhibitors of the IL-6/STAT3 signaling pathway." (PMID 34222014, 2021). "attempted to introduce new therapies based on Th17 lymphocytes which produce IL-17A, IL-17F, IL-21, IL-22, IL-26, IL-6, TNF-α and suppress tumour progression through enhanced antitumor immunity in OC." (PMID 34621670, 2021). "There is a significant decrease of CD8+/CD4+T cells ratio, NK cells, IL-2, and IFN-γ and a significant increase of T regs, IL-6, IL-1β, TNF-α, IL-10, and PGE2 in CUMS group, indicating the inhibition of immunity in the tumor microenvironment." (PMID 34422050, 2021). "Results showed a lead analogue selectively inhibited IL6-dependent activation of JAK2 and STAT3 and suppressed tumour progression both in vitro and in vivo in xenograft lung cancer models." (PMID 34834425, 2021). "M1-like macrophages induced apoptosis and cell cycle arrest of tumor cells by releasing multiple factors including TNF-α, IL-6 and ROS." (PMID 34400883, 2021). "Among these cytokines, IL-6 can stimulate the expression of matrix metalloproteinases (MMPs) by fibroblasts in the TME via inducing EMT, angiogenesis, and tumor growth." (PMID 34868907, 2021). "For example, in a mouse model of aging, senescent stromal cells showed enhanced secretion of IL-6 as part of their SASP, and this resulted in increased levels of suppressive myeloid cells and the creation of a tumor-permissive microenvironment." (PMID 33578753, 2021). "CAFs are also able to influence the immune response to tumours by secreting a plethora of growth factors, cytokines and chemokines such as transforming growth factor-beta (TGF-β), interleukin 6 (IL-6) or CCL2." (PMID 34771746, 2021). "The difference in expression comparing tumor and normal tissues were found to be significant in eight genes (PLAU, EGR1, IL6, EGFR, EZH2, BMP4, CCNB1, NMI)." (PMID 34077304, 2021). "Exosomal miR-21 reduced apoptosis in GC cells, exosomal IL-6 induced metastasis in BC cells, exosomal HSP70 induced tumor progression in MSC cells, and exosomal TGF-β promoted tumor growth in LAMA84 cells." (PMID 33477340, 2021). "ARG1 dependent pro-tumor TAMs stimulate angiogenesis through VEGF and IL6, promote invasion and proliferation via TGFβ and STAT3, and support immunosuppression through IL-10 and TGFβ." (PMID 34222022, 2021). "The abnormal activation of the IL-6-JAK-STAT3 signaling in cancer cells has emerged as an important mechanism for the initiation, development, and progression of various tumor types." (PMID 34551797, 2021). "These cell lines were chosen because they represent increasing tumor cell aggressiveness and invasiveness, respectively, and they each express receptors for OSM/IL-6 cytokines." (PMID 34011405, 2021). "Stromal-derived SDF-1 appears to bind CXCR4 on the surface of the tumor epithelium, thereby activating AKT, ERK, and IL6-mediated survival pathways." (PMID 34336673, 2021).